LPCAT1 (lysophosphatidylcholine acyltransferase 1)
Diseases named in the same sentence as LPCAT1 in open-access papers (continued):
Sharing a sentence is not in itself a finding about the gene and the disease.
meningioma (1 paper, 2017). A generally slow growing tumor attached to the dura mater. "In addition to the TERTp mutations, we identified for the first time in meningioma a fusion that involves the TERT gene (LPCAT1:TERT)." (PMID 29312603, 2017).
myocardial infarction (1 paper, 2025). Gross necrosis of the myocardium, as a result of interruption of the blood supply to the area, as in coronary thrombosis. "These investigations have suggested a potential association between LPCAT1 and increased susceptibility to myocardial infarction, underscoring its significance beyond its known roles in lipid metabolism and inflammation." (PMID 40830908, 2025). "Moreover, recent studies have further implicated LPCAT1 in myocardial infarction, as evidenced by the findings from GWAS and other genetic datasets available in the dbGAP Gene-Trait Associations database." (PMID 40830908, 2025).
myopia (1 paper, 2024). "Significantly, this study unveiled novel insights into the changes in retinal CHRNA7 and LPCAT1 expression associated with myopia, which ZJP administration effectively reversed." (PMID 39625993, 2024). "This investigation provides the first evidence of ZJP’s multifaceted effectiveness in managing myopia, highlighting its impact on multiple components, targets, and pathways, including the novel involvement of LPCAT1 and CHRNA7 in myopia pathogenesis." (PMID 39625993, 2024). "In contrast, the LPCAT1 gene showed a significant drop in expression following a 4-week induction of myopia (P<0.001)." (PMID 39625993, 2024). "By contrast, compared with the NC group, the levels of LPCAT1 (P<0.05) and CHRNA7 (P<0.05) protein decreased after myopia induction for 4 weeks." (PMID 39625993, 2024). "Our data reveal a decrease in LPCAT1 mRNA and protein expression in the LIM group, with an increase observed upon ZJP treatment, underscoring the potential mechanisms through which ZJP might exert protective effects against myopia." (PMID 39625993, 2024). "Therefore, we regard NOS2, LPCAT1, and CHRNA7 as the core targets of ZJP for anti-myopia." (PMID 39625993, 2024).
non-alcoholic steatohepatitis (1 paper, 2020). "In a recent study of western diet-associated non-alcoholic steatohepatitis, LPCAT1 and LPCAT2 are in the top 10 liver genes/transcripts most significantly elevated in mice fed western style diets compared to standard diets." (PMID 32429496, 2020).
Obesity (1 paper, 2018). Accumulation of substantial excess body fat. "On the other hand, untargeted lipidomics analysis showed that phospholipids of specific molecular species were significantly reduced in the colonic epithelium from young obese mice, in keeping with obesity-associated dysregulation of phospholipid metabolism genes, such as Lpcat1 and Lpcat4." (PMID 29346762, 2018).
oral cancer (1 paper, 2015). "LPCAT1 may contribute to tumoral growth and metastasis in oral cancer." (PMID 25803864, 2015).
renal carcinoma (1 paper, 2025). A carcinoma arising from the epithelium of the renal parenchyma or the renal pelvis. "We utilized a renal cancer cell line model, comparing LPCAT1 expression in three VHL-mutant cell lines (A-498, 786-O, and OS-RC-2) against the HK-2 control." (PMID 39781455, 2025).
respiratory failure (1 paper, 2014). The significant impairment of gas exchange within the lungs resulting in hypoxia, hypercarbia, or both, to the extent that organ tissue perfusion is severely compromised. "Studies on genetically manipulated mice indicated that newborn mice bearing a hypomorphic allele of LPCAT1 showed varying levels of perinatal mortality from respiratory failure; LPCAT1 mRNA levels were reduced and directly correlated with LPCAT1 activity, saturated PC content, and survival." (PMID 25415055, 2014).
Retinal dystrophy (1 paper, 2024). Retinal dystrophy is an abnormality of the retina associated with a hereditary process. "Animal models of retinal dystrophy (rd11 and B6-JR2845) revealed that LPCAT1 was responsible for maintaining specific cell membrane lipidic composition and retinal homeostasis during the degeneration process." (PMID 38542059, 2024).
sudden cardiac arrest (1 paper, 2019). Unexpected rapid natural death due to cardiovascular collapse within one hour of initial symptoms. "The protein coded by LPCAT1 is involved in the remodelling of phospholipids and has been associated with risk of sudden cardiac arrest, whereas the protein coded by SLC25A20 is involved in the transport of fatty acids across the mitochondrial membrane." (PMID 30841568, 2019).
vascular tumour (1 paper, 2022). "The KPNA2, LPCAT1, KIF2C, and SPP2 genes were statistically correlated with pathological stage, histologic grade, ECOG, vascular tumour cell type, and tumour status." (PMID 35915607, 2022).
cancer (74 papers, 2014 to 2025). A tumor composed of atypical neoplastic, often pleomorphic cells that invade other tissues. "Dysregulation of LPCAT1 has been linked to cancer cell genetic alterations, abnormal metabolism, plasma membrane restructuring, and malignant transformations with a poor prognosis." (PMID 40830908, 2025). "Amplification of LPCAT1 is commonly observed in cancer and is linked to unfavourable patient survival rates." (PMID 40259435, 2025). "Elevated levels of LPCAT1 were associated with poor outcomes in cancer patients and induced resistance to gefitinib in lung adenocarcinoma cells (LUAC) and to paclitaxel in breast cancer." (PMID 39624081, 2024). "Elevated LPCAT1 expression is consistently associated with a poorer prognosis in patients with these cancers." (PMID 38893234, 2024). "LPCAT1 has been linked with the progression of various types of cancer via the reprogramming of cholesterol metabolism or regulating oncogenic signaling." (PMID 37999208, 2023). "LPCAT1 has been shown to be associated with various cancers and play an important role in the occurrence and development of various tumors." (PMID 36307879, 2022). "These functions greatly contribute to cancer metastasis and malignancy, which further support our observations that high levels of LPCAT1 are associated with poor prognosis in ESCC patients." (PMID 34518524, 2021). "Furthermore, aberrant expression of LPCAT1 was closely associated with the progression of various cancers." (PMID 40555906, 2025). "Of notice, in GC, we found the cancer-associated genes LPCAT1 and RAD51C over-expressed in females." (PMID 32849808, 2020). "Lysophosphatidylcholine acyltransferase 1 (LPCAT1) has been implicated with various cancer types." (PMID 31533087, 2019). "According to the PFI analysis, LPCAT1 expression was significantly correlated with five types of cancer, with READ, SKCM, and PAAD being protective factors and with CESC, KICH, KIRC, LUSC, PRAD and THCA being risk factors." (PMID 40555906, 2025). "Pan-cancer investigation using TIMER2.0 online platform revealed that LPCAT1 expression is elevated in various types of tumors, particularly in ccRCC, where expression levels in tumor tissues greatly exceed those in normal tissues." (PMID 39781455, 2025). "Lysophosphatidylcholine acyltransferase 1 (LPCAT1), an enzyme critical for phospholipid remodeling, has emerged as a regulator of lipid metabolism and cancer progression." (PMID 41358198, 2025). "Given the pivotal role of immune responses not only in PCOS but also in cancer pathogenesis, we employed GSTP1 and LPCAT1 to investigate potential associations between these two disease categories." (PMID 40555906, 2025). "The cited data show that LPCAT1 is important in the tumorigenic processes of many types of cancer, which makes it a potential therapeutic target for cancer treatment." (PMID 38893234, 2024). "Lysophosphatidylcholine acyltransferase 3 (LPCAT3) promotes the induction of ferroptosis, while lysophosphatidylcholine acyltransferase 1 (LPCAT1) triggers ferroptosis evasion in cancer cells." (PMID 39624080, 2024). "Cancer cells convert LPC to produce various PCs via LPC acyltransferase 1 (LPCAT1), and the PCs are utilized for plasma membrane remodeling." (PMID 37147444, 2023). "Recently the enzyme Lysophosphatidylcholine acyltransferase 1 (LPCAT1) has emerged as a novel diagnostic marker in HCC, being overexpressed in different cancers, including HCC." (PMID 38110968, 2023). "We explored the expression levels of AGPAT5, LCLAT1, and LPCAT1, the three core genes of the prognostic model, in normal and pan-cancer tissues based on XENA-TCGA-GTEx datasets." (PMID 36845084, 2023).
cancer (continued). "In this research, expression analysis and survival analysis for LPCAT1 in various human cancers were firstly conducted." (PMID 35615532, 2022). "Consistent with this, lysophosphatidylcholine acyltransferase LPCAT1 deletion significantly altered the bulk lipid composition and regulated oncogenic growth factor signaling of cancer cells." (PMID 35906240, 2022). "Firstly, the expression level of LPCAT1 in eighteen types of cancers was evaluated, which found that LPCAT1 was significantly upregulated in 16 cancer types other than KICH and LUSC, compared to corresponding normal samples." (PMID 35615532, 2022). "Next, survival analyses for the prognosis of cancer patients further proved the potential role of LPCAT1 in LIHC." (PMID 35615532, 2022). "Highly expressed LPCAT1 was observed in several types of cancer tissues compared with normal tissues." (PMID 35915607, 2022). "Previous studies demonstrated that LPCAT1 plays a vital role in different types of human cancer, including LIHC." (PMID 35615532, 2022). "Since LPCAT1 overexpression is also observed in aggressive forms of a broad variety of other cancer types a general role of this protein during tumor progression has been suggested." (PMID 34148155, 2021). "During the process of tumour initiation and progression, increased LPCAT1 promotes the synthesis and remodelling of lipids in the lipid-dependent membrane structures of rapidly proliferating cancer cells." (PMID 34419067, 2021). "LpCat1 was reported to be highly expressed and exert pro-tumorigenic effect in a variety of cancers, including HCC." (PMID 34178664, 2021). "While not universally recognized as an oncogene, growing evidence links LPCAT1 overexpression to cancer progression, metastasis and recurrence in oral, kidney, breast, gastric, and lung cancers." (PMID 34033669, 2021). "Mounting evidence demonstrated that LPCAT1 participates in the pathophysiological process of cancer by dysregulating lipid metabolisms." (PMID 34419067, 2021). "In line with our finding, up-regulation of Lpcat1 and Faah or down-regulation of Dgka and Pip5k1b has been reported in other human cancers." (PMID 34202989, 2021). "A growing number of studies have demonstrated that LPCAT1 plays a significant role in cancer pathogenesis." (PMID 34518524, 2021). "To explore the underlying molecular mechanism of LpCat1 in HCC, we detected a series of cancer-related genes." (PMID 34178664, 2021). "The results showed that the gene expression and protein levels of LPCAT1 were significantly higher in tumor tissues than in normal tissues adjacent to cancer in patients with ESCC." (PMID 34518524, 2021). "So far, LPCAT1 overexpression has been reported to promote cancer progression, metastasis and recurrence in multiple tumors." (PMID 34698001, 2021). "That this relationship retained high statistical significance in various analyzed cancer subgroups defined by an identical status of morphologic or molecular parameters argues for a particular strong role of LPCAT1 for tumor growth." (PMID 31533087, 2019). "In cancer, detectable LPCAT1 immunostaining was seen in 1,619 of our 1,774 (91.3%) tumors and was considered weak in 48.1%, moderate in 28.7% and strong in 14.4% of tumors." (PMID 31533087, 2019). "That LPCAT1 overexpression is also observed in aggressive forms of a broad variety of other cancer types suggests a general role of this protein during tumor progression." (PMID 31533087, 2019). "It is noteworthy that the 12% of cancers classified as “strong LPCAT1 expressers” behaved significantly worse than the other cancers, especially when the clinical outcome (overall survival) was taken into account." (PMID 31533087, 2019). "Strong LPCAT1 was associated with BRE grade, tumor cell proliferation and overall survival in all cancers and in the subgroup of NST cancers (p<0.0001, each)." (PMID 31533087, 2019).
cancer (continued). "The association between strong LPCAT1 expression and poor prognosis was even more pronounced in the subgroup of NST cancers (p=0.0006) and in the nodal positive subset (p=0.0022) but was not seen in nodal negative cancers (p=0.1716)." (PMID 31533087, 2019). "LPCAT1 overexpression has been noted in many other types of cancer including breast and colorectal cancers, and the level has often been considered clinically relevant in tumorigenesis." (PMID 29348849, 2017). "Several studies have reported that LPCAT1 is overexpressed in several kind of cancer tissues and contributes to the development and progression of cancers." (PMID 28494778, 2017). "Past studies have reported overexpressed LPCAT1 in cancers and mentioned the close interaction between overexpressed LPCAT1 and malignancies, such as vigorous tumoral growth, frequent metastasis, early recurrence, and poor prognosis." (PMID 25803864, 2015). "To explain the relation between overexpressed LPCAT1 and cancer malignancy, we investigated the intracellular PAF concentration." (PMID 25803864, 2015). "Notably, several cancer-associated genes are located within a 1 Mb proximity including CLPTM1L, TERT, BRD9, TRIP13, NKD2, LPCAT1, and IRX4." (PMID 40278994, 2025). "GSPT1 (G1 to S phase transition 1) functions as a translation termination factor critical for cell cycle regulation and is vital for cell cycle regulation, while LPCAT1 is key for lipid remodeling and is associated with cancers and nontumor diseases." (PMID 40555906, 2025). "LPCAT1 (Lysophosphatidylcholine acyltransferase 1) is an enzyme involved in phospholipid biosynthesis and remodeling, playing a pivotal role in the lipid remodeling and various cancers, including OSCC." (PMID 40538852, 2025). "Moreover, the expression of LPCAT1 was found to be significantly elevated, specifically in BM samples, suggesting malignant cancer cells with upregulated LPCAT1 were prone to migrate to the brain." (PMID 38589859, 2024). "We analyzed LPCATs family genes (LPCAT1-4) expression levels in pan-cancer." (PMID 37294538, 2023). "Moreover, available information suggests that several other TRAF3-regulated metabolic enzymes (e. g., Lpcat1, Pygl, Hk2, and Mthfd1) are also targetable points in cancers." (PMID 36776285, 2023). "It was found that LPCAT1-4 expression levels were elevated in most kinds of cancer types." (PMID 37294538, 2023). "Our results indicate that LPCAT1 is overexpressed in most human tumors, suggesting that LPCAT1 may play a key promoting role in the development of these cancers including HCC." (PMID 36307879, 2022). "LPCAT1 elevation across cancer types suggests that the increase in membrane saturated PL levels might prevent lipid peroxidation and ferroptosis in cancer cells, thereby facilitating tumor growth." (PMID 36009491, 2022). "We believe that our study provides more insights into the role of LPCAT1 in EC, and LPCAT1 may be a potential novel cancer therapeutic target for EC." (PMID 35880567, 2022). "Since knockdown of Lpcat1 expression leads to tumor cell death, Lpcat1-dependent cell survival of mature photoreceptor cells and cancer cells may show some metabolic similarities." (PMID 35452679, 2022). "Since high LPCAT1 expression exists in a variety of cancers, LPCAT1 may serve as a potential target of targeted therapy." (PMID 35399731, 2022). "In this study, expression analysis and survival analysis for LPCAT1 in pan cancers were first performed by using The Cancer Genome Atlas (TCGA) data, which suggested that LPCAT1 might be a potential LIHC oncogene." (PMID 35615532, 2022). "Previous studies have shown that the LPCAT1-mediated production of saturated PC is required for the proper functioning of pulmonary surfactant in the lung and trafficking of growth factor receptors in cancer cells." (PMID 35452679, 2022).